STAT3 (signal transducer and activator of transcription 3)
Diseases named in the same sentence as STAT3 in open-access papers (continued):
Sharing a sentence is not in itself a finding about the gene and the disease.
lung carcinoma (continued). "On this basis, we speculated that HJC0152, a STAT3 inhibitor, might be a promising therapeutic agent for treating lung cancer, including NSCLC." (PMID 32022328, 2020). "In conclusion, dioscin may act as a new anti‐tumour agent by inhibiting TAMs via JNK and STAT3 pathways in lung cancer." (PMID 32618105, 2020). "In addition, STAT3 was identified to be critically involved in shaping the lung cancer TME by driving tumor promoting inflammation and evasion of anti-tumor immunity." (PMID 32365499, 2020). "Additionally, William’s syndrome transcription factor (WSTF), a tyrosine kinase, promotes tumor growth via activation of AKT and STAT3 in lung cancer." (PMID 31952344, 2020). "Moreover, our recent work showed that FZKA induced lung cancer cell apoptosis via STAT3/Bcl-2/Caspase-3 pathway." (PMID 32489321, 2020). "A009 extracts were able to decrease STAT3 phosphorylation in lung cancer cells." (PMID 32224910, 2020). "Furthermore, STAT3 signaling is believed to promote lung cancer cell proliferation and migration and stimulate hepatocyte compensatory proliferation." (PMID 33177520, 2020). "Notably, NSCLC development was enhanced by circ_ZNF124, which was targeted by miR-337-3p directly to downregulate the JAK2/STAT3 signaling pathway, thereby providing indirect evidence of the role of the GJ–astroglial-STAT3 axis in lung cancer brain metastasis." (PMID 33425756, 2020). "Based on the findings of the present study, it can be concluded that microRNA-608 may inhibit cell proliferation, migration, and invasion of lung cancer by targeting BRD4 through the JAK2/STAT3 pathway." (PMID 31621555, 2020). "Our hypothesis predicts that expressing uSTAT3 and STAT3 knockdown would have opposite effects on lung cancer growth." (PMID 32087696, 2020). "Furthermore, another study found that a conditional epithelial cell STAT3 knockout in mouse models of K‐ras mutant lung cancer resulted in different tumor burdens between male and female mice." (PMID 32710512, 2020). "Maybe, besides phosphorylation, some other mechanisms that activate STAT3 following stimulation of nicotine exist in lung cancer cells." (PMID 31956373, 2020). "The sensitivity of nonsmall cell lung cancers to taxane also might be attributable to STAT3 targeted by miR-337-3p60." (PMID 32934214, 2020). "Exosome-mediated transfer of miR-193a-3p, miR-210-3p and miR-5100, could promote invasion of lung cancer cells by activating STAT3 signalling-induced EMT." (PMID 30866952, 2019). "The IL-6—STAT3 signalling axis has emerged as a key contributor to carcinogenesis in a number of cancers, often resulting in increased IL-6 expression as observed in lung cancer and head and neck cancers." (PMID 31226168, 2019). "In addition, aberrant Akt was found to contribute to maintaining stemness through a NF-kB/IL-6/STAT3 pathway in lung cancer cells." (PMID 31696055, 2019). "Most proinflammatory factors activate STAT3, and chitinase 3-like 1 that is a downstream gene of the STAT3 signaling pathway is a potential biomarker to predict inflammatory lung cancer in a STAT3-induced mouse lung cancer model." (PMID 31832112, 2019). "We next investigated whether BT could modulate constitutive STAT3 activation in human prostate and lung cancer cell lines." (PMID 31575007, 2019). "Overall, our data demonstrate PDLIM2 epigenetic repression and RelA/STAT3 regulation of MHC-I, MDR1 and cancer-related genes as a previously unknown mechanism underlying lung cancer development and resistance to PD-1 blockade and chemotherapy." (PMID 31757943, 2019). "A recent study by Caetano and colleagues demonstrated that female animals, in the context of Il-6 and Stat3 pro-tumor inflammatory signaling, displayed differential anti-lung cancer immune responses, evidenced by levels of tumor infiltrating lymphocytes, compared with males." (PMID 31001473, 2019).
lung carcinoma (continued). "Taken together, these findings suggest flavonoid compounds may well be responsible for MH-mediated inhibition of the IL-6/STAT3 signaling pathway in human breast and lung cancer cells." (PMID 31491838, 2019). "MVP may suppress tumor cell growth and facilitate apoptosis of lung cancer cell through inhibition of STAT3 signaling pathway." (PMID 31092229, 2019). "Increased expression of IL-22 and its receptor IL-22R1 and increased activation of STAT3 in human lung cancer cell lines mediate resistance to standard chemotherapy, which could be linked to the role of IL-22 in induction of stemness properties." (PMID 32039025, 2019). "Research showed that CAV1 can mediate lung cancer cells apoptosis through STAT3 pathway." (PMID 31296840, 2019). "The pro-inflammatory cytokine IL-6 is of relevance in lung cancer biology, pathology, and therapy, especially as it interacts with and activates the signal transducer and activator of transcription (STAT)-3, which is constitutively activated in various types of malignancies." (PMID 31547048, 2019). "Surprisingly, we found that the enrichment of STAT3 target gene sets is associated with reduced KLF3 expression in lung cancer, suggesting that KLF3 may be involved in the STAT3 signaling pathway." (PMID 31486564, 2019). "Moreover, CDK1/GP130/STAT3 signaling were elevated in lung cancer tissues compared with adjacent normal lung tissues." (PMID 30931929, 2019). "It was also demonstrated that leptin promoted the development of lung cancer via JAK/STAT3 pathway." (PMID 31506433, 2019). "Our results may contribute to the development of potential strategies to target GP130/STAT3 signaling and suppress lung cancer via CDK1 blockade and iron deprivation." (PMID 30931929, 2019). "In addition, gene knockdown and RNAseq were used to investigate molecular mechanisms through which STAT3 regulates tumor progression and the survival in lung cancer." (PMID 31619200, 2019). "However, our study highlights the constitutive activation of STAT3 in lung cancer cells and ACHP induced cell death via blocking oncogenic STAT3 signaling." (PMID 31847229, 2019). "To examine whether T21 was also able to block STAT3 signaling after stimulating with one of its upstream ligands, we first analyzed the IL-6 effects on STAT3 phosphorylation in lung cancer cells." (PMID 31412593, 2019). "Loading a STAT3 inhibitor on SLNs is of importance in combating lung cancer cells." (PMID 31569687, 2019). "Furthermore, it is increasingly evident that the JAK2/STAT3 signaling pathway plays a critical role in tumor growth, proliferation, and metastasis of several malignancies, including lung cancer." (PMID 31492006, 2019). "In addition, in a mouse lung cancer xenograft model, resveratrol significantly inhibits the tumor growth, decreasing cell proliferation and expression of p-STAT3 in tumor tissues." (PMID 31035454, 2019). "Moreover, in lung cancer, a reduction in SOCS3 enhances the expression of STAT3 thus causing the progression of cancer cells." (PMID 31569687, 2019). "Furthermore, it is increasingly evident that the JAK2/STAT3 signaling pathway plays a critical role in tumor growth, proliferation, and the metastasis of several malignancies, including lung cancer." (PMID 31492006, 2019). "A number of studies have documented curcumin mediated anti-proliferative effect in lung cancer cells via modulation of various molecular targets such as STAT-3, EGFR, Forkhead Box O3 (FOXO3a), Eukaryotic Initiation Factors (eIFs), and Transforming Growth Factor-Beta (TGF-β)." (PMID 31817718, 2019). "Down-regulated STAT3 promoted the sensitivity of lung cancer cells to gefitinib." (PMID 31777595, 2019). "Based on the findings above, we hypothesized that through restoring PDLIM2 expression to repress RelA and STAT3 activation, epigenetic drugs render lung cancer vulnerable to chemotherapeutic drugs and anti-PD-1." (PMID 31757943, 2019).
lung carcinoma (continued). "Furthermore, it is assumed that in cancer cells the AhR-mediated transcription of IL6 leads to the autocrine activation of IDO expression via STAT3 (AhR-IL6-STAT3 loop), which is associated with a poor prognosis in lung cancer." (PMID 31417567, 2019). "In lung cancer, co-repression of STAT3 and ARHGAP35 signaling is conducive for cancer treatment." (PMID 31130822, 2019). "While activated STAT3 protein in normal cells is well controlled and has a short lifespan, the activated STAT3 protein in cancer cells including lung cancer is continuously active leading to uncontrolled proliferation, apoptosis resistance, as well as sustained angiogenesis." (PMID 31817718, 2019). "We subsequently demonstrated that WA could inhibit the growth of lung CSCs, decrease side population cells, and inhibit lung cancer spheroid-forming capacity, at least through downregulation of mTOR/STAT3 signaling." (PMID 31319622, 2019). "More importantly, we provided new insights into the KLF3/STAT3 signaling pathway in lung cancer." (PMID 31486564, 2019). "In addition, western blotting analysis of lysate from lung cancer cells treated with STX-0119 showed that STX-0119 decreased the expression of STAT3 target proteins such as c-Myc, cyclin D1, and survivin in a concentration-dependent manner." (PMID 32257917, 2019). "Interestingly enough, SOCS3 is known to mediate the JAK/STAT3 signaling pathway to regulate cell proliferation, differentiation, and apoptosis in lung cancer." (PMID 31130822, 2019). "We first assessed the activation of the STAT3 pathway in response to CM from four lines of lung cancer cells and observed that STAT3 signalling was activated in quiescent ADSCs from healthy donors exposed to lung cancer cell CM for 2 days." (PMID 31196220, 2019). "Still, in all cases high Src levels, either endogenous or exogenously expressed, eliminated GJIC, while Stat3 inhibition eliminated junctional permeability in any of the lung cancer lines examined, in agreement with data from mouse or rat fibroblasts or epithelial cells." (PMID 30717267, 2019). "We then examined whether PDLIM2 suppresses lung cancer through repressing the transcription factors NF-κB RelA and/or STAT3." (PMID 31757943, 2019). "Therefore, targeting STAT3 is considered a potential strategy for overcoming EGFR-TKI resistance associated with KRAS and T790 M mutations in lung cancers." (PMID 31619200, 2019). "CDK1 and STAT3 are essential for iron-mediated colony formation in lung cancer cell lines." (PMID 30931929, 2019). "Interestingly, our recent work demonstrated that while IL-6 is associated with lung cancer diagnosis in both EAs30 and AAs31, the effect size was considerably larger among AAs, which is further evidence that this IL-6/JAK2/STAT3 pathway is important among AAs." (PMID 31844068, 2019). "Ablation of IL-6 or STAT3 suppressed the extent of lung cancer in this model." (PMID 31694340, 2019). "Exosome-mediated transfer of miR-193a-3p, miR-210-3p and miR-5100, could promote invasion of lung cancer cells by activating STAT3 signaling-induced EMT." (PMID 30866952, 2019). "Thus, STAT3 has been regarded as a key target for lung cancer prevention, and inhibition of STAT3 signal showed great anticancer and antiangiogenic effects in vitro and in vivo." (PMID 29456509, 2018). "Moreover, increased STAT3 activity is correlated to poorer overall survival of lung cancer patients." (PMID 29456509, 2018). "Thus we reasoned that STAT3 regulated the expression of Bcl-2 family in the FZKA-treated lung cancer cells." (PMID 30046347, 2018). "Our data indicate that PLOD3 regulates lung cancer metastasis directly via STAT3 signaling." (PMID 30442941, 2018). "MALAT1-mediated upregulation of STAT3 also correlates with its reported role in enhancing the expression of MRP1 (ATP binding cassette subfamily C member 1) and MDR1 (ATP binding cassette subfamily B member 1) through STAT3 activation, in turn driving cisplatin-resistance in lung cancer." (PMID 29702599, 2018).
lung carcinoma (continued). "Moreover, FZKA induced lung cancer cell apoptosis significantly with concomitant induction of p27, reduction of Jab1 protein expression, and phosphorylation of STAT3." (PMID 30046347, 2018). "Together, our findings suggest that chemotherapy may activate immune response mechanisms such as IFNα, IFNγ, STAT3, and TNFα in lung cancer, which may generate a favorable tumor microenvironment for subsequent response to checkpoint immunotherapy." (PMID 29871672, 2018). "To determine whether PLOD3 and STAT3 coordinate to promote lung cancer metastasis in patients, we analyzed the potential correlation between PLOD3 and STAT3 expression levels in lung cancer patients." (PMID 30442941, 2018). "Furthermore, analysis of the publicly available microarray datasets revealed a correlation between PLOD3 and STAT3 mRNA levels in lung cancer patients." (PMID 30442941, 2018). "Among its multiple contributions to intracellular signaling in nonmalignant cells and cancer cells, signal transducer and activator of transcription 3 (STAT3) is known when activated to promote radioresistance in a variety of tumors, including gliomas and lung cancer." (PMID 30651936, 2018). "Nevertheless, these two studies suggest that Stat3 may function as a tumor suppressor in lung cancer under different genetic scenarios." (PMID 29126425, 2017). "We hypothesized that there could be a correlation between ING5 tumor suppressive function and PI3K/Akt and STAT3 signaling in lung cancer." (PMID 28903339, 2017). "The results of this meta-analysis suggested that p-STAT3 overexpression may be a poor prognosis biomarker in lung cancer (HR: 1.23; 95% CI: 1.04–1.46; P = 0.02)." (PMID 28797050, 2017). "BBR has been shown to suppress STAT3 activity in human lung cancer cells." (PMID 28611316, 2017). "The elevated OPN in lung cancer cells activates STAT3 pathways which stimulate OPN expression." (PMID 29254164, 2017). "Recently, an in vitro cell model identified the repressive effect of an ASO (AZD9150) on reducing signal transducer and activator of transcription 3 (STAT3) expression by directly targeting its transcripts, which exerts antitumor impacts on lung cancer and lymphomas." (PMID 29283381, 2017). "6-OAP inhibited constitutively activated STAT3, suppressed IL-6-induced pSTAT3, and triggered apoptosis and suppressed migration of lung cancer cells in vitro and showed potent anti-lung cancer activity in vivo." (PMID 27835873, 2017). "Thus, in contrast to c‐kit and c‐myc oncogene expression, STAT3 expression in NK cells was significantly higher in patients with lung cancer than in healthy donors." (PMID 28695716, 2017). "STAT3 is a critical protein in tumor metastasis, including that of lung cancer." (PMID 29207614, 2017). "Our study suggests that Hdac7 promotes lung tumorigenesis by inhibiting Stat3 activation via deacetylating Stat3 and may shed a light on the design of new therapeutic strategies for human lung cancer." (PMID 29126425, 2017). "Given that 6-OAP is a Skp1 inhibitor, our data suggest that this compound may target Skp1 and STAT3 to suppress Skp2, augmenting its anti-lung cancer activity." (PMID 27835873, 2017). "Taken together, CAFs may induce lung cancer cell EMT via secreting IL-6 that activate STAT3 and subsequently inhibit miR-33b which locates in SREBP1 gene." (PMID 29383119, 2017). "However, STAT3 expression was different in NK cells from lung cancer patients and patients with gastric, sigmoid, and colon cancer." (PMID 28695716, 2017). "We also observed a weak induction of Stat3, which may play oncogenic and oncosuppressive roles in lung cancer." (PMID 27966456, 2017). "Furthermore, STAT3 expression in NK cells was significantly different in lung cancer patients and healthy donors." (PMID 28695716, 2017).
lung carcinoma (continued). "Therefore, we conducted this meta-analysis to elucidate the association between p-STAT3 overexpression and the overall survival of lung cancer patients, as well as between p-STAT3 overexpression and other clinicopathological characteristics." (PMID 28797050, 2017). "Given the stimulatory role of IL-6 on JAK/STAT signaling, IL-6/JAK/STAT3 signaling may be involved in lung cancer progression." (PMID 28819126, 2017). "The role of STAT3 in lung cancer development appears complex." (PMID 29126425, 2017). "However, two groups of patients demonstrated a significant difference in STAT3 expression in NK cells: MFI results were 5070 ± 2951 in lung cancer patients (n = 10) versus 827 ± 614 in patients with gastric, sigmoid, and colon cancer (n = 4) (P = 0.016)." (PMID 28695716, 2017). "Taken together, these results suggest that endogenous EFs in the tumor micro-environment might play an important role in lung cancer metastasis by guiding cell migration through a Cav-1/STAT3-mediated signaling pathway." (PMID 29221162, 2017). "Inactivation of STAT3 overcomes taxane resistance in various cancers, including lung cancer cells." (PMID 29072615, 2017). "Previous study also revealed that Met in combination with first-generation TKI effectively increased the sensitivity of TKI-resistant lung cancer cells and blocked tumor growth in xenografts, associated with decreased IL-6 secretion, reversal of EMT and dampened IL-6/STAT3 signaling." (PMID 29312591, 2017). "increased signalling via signal transducer and activator of transcription 3 (STAT3), extracellular regulated kinases (ERK) and epidermal growth factor receptor (EGFR), inactivation of phosphatase and tensin homolog (PTEN) and the ALK mutation in lung cancer." (PMID 28122336, 2017). "Our data revealed a novel mechanism, by which STAT3 is persistently activated in lung cancer." (PMID 28830450, 2017). "Mitochondrial dysfunction and oxidative stress of repeated exposure to urethane associated with over stimulation of IFN-γ-producing cells, CD11b + Gr-1 + phenotype, overexpression of NF-кB, COX-2, STAT3, IL-6 and cyclin D1 resulted in chronic inflammation and lung cancer." (PMID 28240047, 2017). "For example, Grivennikov and Karin reported that autocrine IL-6 as an important activator of oncogenic STAT3 was implicated in lung adenocarcinomas; furthermore, SOCS3 has been found to be suppressed by hypermethylation in lung cancer cells, which promoted the progression of lung cancer." (PMID 28591704, 2017). "Thus, our results add to the notion that STAT3 activation by Cav-1 is required for lung cancer electrotaxis." (PMID 29221162, 2017). "Therefore, 6-OAP inhibited both Skp1 and STAT3 to repress Skp2, exhibiting inhibitory effects on lung cancer cell proliferation and survival." (PMID 27835873, 2017). "Additionally, we also investigated the effect of STAT3 pathway inhibition in lung cancer cells to understand the importance of IL-6/JAK/STAT3 pathway." (PMID 28830450, 2017). "STAT3 is abundantly expressed in lung cancer cells and involved in the development of cancer." (PMID 28608828, 2017). "For example, we are investigating the effect of midazolam on lung cancer cells (A549), and we found that midazolam could induce the apoptosis of A549 cells through regulating signal transducer and activator of transcription 3 (Stat3) signaling pathway." (PMID 28706559, 2017). "In addition, the levels of both miR-218 host genes and the components of IL-6/STAT3 pathway correlated with prognosis of lung cancer patients." (PMID 28830450, 2017). "We tested the expression of STAT3 in several cell lines by Western blot, and found that the expression of pSTAT3 in lung cancer lines (SPC-A-1, EKVX, HCC827, H1975, H292, A549, 95D, and L78) was higher than in normal bronchial epithelial (HBEpiC, Beas-2B, 16HBE) or lung fibroblast (HLF) cell lines." (PMID 27835873, 2017).